TLR9 (toll like receptor 9)
Diseases named in the same sentence as TLR9 in open-access papers (continued):
Sharing a sentence is not in itself a finding about the gene and the disease.
glioma (continued). "Therefore, ADV infection likely triggers TLR9/MYD88 signaling, which upregulated NEAT1 and activated STAT3, and activated STAT3 further upregulates NEAT1 to form a positive-feedback loop, and promotes GSCs formation from primary glioma cells." (PMID 32843056, 2020). "However, in our system, CpG-ODN appeared not able to trigger the stemness signaling in glioma cells, although it has been widely employed as an agonist of TLR9." (PMID 32843056, 2020). "The exact pathophysiological role of TLR9 in glioma is not known but it may represent a useful prognostic biomarker in glioma patients." (PMID 20696081, 2010). "In our research, a different glioma cell line(U87 cells) were used to ensure whether or not TLR9 is responsible for the invasive of glioma cells induced by CpG ODN." (PMID 20696081, 2010). "Moreover, in glioma cells, insulin-like growth factor 1 (IGF-1) could induce TLR9 expression through hypoxia-induced factor 1 alpha signaling, which further leads to secretion of cytokines IL-1β, IL-6, IL-8, and CXCR4 (a chemokine receptor that plays an important role in cell migration)." (PMID 34715891, 2021). "In this research, we found that non-CpG ODN(ODN2006 control) can also increase the invasion of glioma cells through TLR9 signaling pathway, which indicated that non-CpG ODNs (ODNs from in vivo cells such as dying tumor cells) may also be able to increase the invasion of glioma through TLR9 pathway." (PMID 20696081, 2010).
cervical carcinoma (38 papers, 2012 to 2025). A carcinoma arising from either the exocervical squamous epithelium or the endocervical glandular epithelium. "A meta-analysis in 2018 found that SNP rs187084 in TLR-9 presented a significant correlation to the risk of cervical cancer." (PMID 41374999, 2025). "More recent meta-analyses showed that TLR9 rs187084 polymorphism, among others, is significantly associated with increased susceptibility to cervical cancer." (PMID 38850110, 2024). "The CT and TT genotypes within TLR9 rs187084 were previously reported to be correlated with an increased risk of cervical cancer, while the CT variant was shown to be protective against severe bronchiolitis." (PMID 35877427, 2022). "The variant genotypes of TLR4 rs1156889 and TLR9 rs187084 and rs1927911 SNPs were found to be associated with the increased risk of developing cervical cancer among Indian women." (PMID 35330409, 2022). "Another study, performed in the Polish population, showed TLR9 rs352140 as a possible genetic risk factor for cervical cancer." (PMID 34828331, 2021). "We performed this meta-analysis to explore the role of XRCC3 rs861539, MTHFR rs1801133, IL-6 rs1800795, IL-12B rs3212227, TNF-α rs1800629 and TLR9 rs352140 polymorphism with susceptibility to cervical carcinoma." (PMID 34837895, 2021). "In this meta-analysis, we explore the role of XRCC3 rs861539, MTHFR rs1801133, IL-6 rs1800795, IL-12B rs3212227, TNF-α rs1800629, and TLR9 rs352140 polymorphisms in susceptibility to cervical cancer." (PMID 34837895, 2021). "Their results showed that mutant alleles of TLR2 rs3775290, TLR4 rs7873784, and TLR9 rs352140 were associated with increased cervical cancer risk." (PMID 34837895, 2021). "In another study in India showed the TLR4 and TLR9 polymorphisms and haplotypes with hrHPV infection and cervical cancer risk." (PMID 34837895, 2021). "In this meta-analysis, the association of XRCC3 rs861539, MTHFR rs1801133, IL-6 rs1800795, IL-12B rs3212227, TNF-α rs1800629 and TLR9 rs352140 polymorphisms with susceptibility to cervical carcinoma was assessed by including all relevant studies." (PMID 34837895, 2021). "In a study concerning cervical cancer, it was registered that TLR4 haplotype GTAC and TLR9 haplotype GATC are associated with an increased risk of cervical cancer, while TLR4 haplotype GCAG is associated with a decreased risk." (PMID 34439871, 2021). "TLR4 haplotype GTAC and TLR9 haplotype GATC were associated with the increased risk of cervical cancer while TLR4 haplotype GCAG was associated with the decreased risk." (PMID 31278284, 2019). "In conclusion, the present study revealed association of TLR4 and TLR9 polymorphisms and haplotypes with hrHPV infection and cervical cancer risk." (PMID 31278284, 2019). "Our results suggest moderate to strong impact of TLR4 and TLR9 polymorphisms in susceptibility to hrHPV infection and cervical cancer." (PMID 31278284, 2019). "Reports on the influence of TLR4 and TLR9 single nucleotide polymorphisms (SNPs) in cervical cancer susceptibility are limited as well as conflicting." (PMID 31278284, 2019). "Although our results suggest a significant role of TLR4 and TLR9 polymorphisms in cervical cancer, the study has some vital limitations too." (PMID 31278284, 2019). "The TLR4 haplotype GTAC was linked with a significant increase in cervical cancer risk in addition to the TLR9 haplotype GATC that also showed association with increased HPV 16 and 18 infections." (PMID 31278284, 2019). "The present study was therefore designed to ascertain the role of TLR4 and TLR9 SNPs and haplotypes to hrHPV infection and cervical cancer susceptibility." (PMID 31278284, 2019). "A similar association of TLR9 rs187084 polymorphism with an increased risk of cervical cancer was reported among Polish and Chinese women." (PMID 31278284, 2019).
cervical carcinoma (continued). "Our results on TLR9 rs187084 polymorphism are in good agreement with the recent meta-analyses that supported a significant role of rs187084 in cervical cancer risk." (PMID 31278284, 2019). "It has been noted that the TLR9 gene is polymorphic and associated with various cancers, including cervical cancer, prostate cancer, oesophageal cancer, gastric cancer, breast cancer, colorectal carcinoma, and lymphoma." (PMID 30147445, 2018). "Pooled odds ratios and 95% confidence intervals were employed to evaluate the strength of the associations between Toll-like receptor 9 polymorphisms and cervical cancer risk." (PMID 30147445, 2018). "Data revealed that TLR9 rs187084 was related to cervical cancer risk in the Chinese Han population in the dominant model (OR = 1.22, p = 0.05) and heterozygous genetic model (OR = 1.28, p = 0.02)." (PMID 30147445, 2018). "This meta-analysis systematically reviews the association between Toll-like receptor 9 polymorphisms and the risk of cervical cancer." (PMID 30147445, 2018). "In recent years, a number of studies have focused on TLR9 gene polymorphisms and cervical cancer susceptibility, but the conclusions are questionable." (PMID 30147445, 2018). "Data revealed that TLR9 rs187084 was related to cervical cancer risk of Chinese Han population in the dominant model (OR = 1.22, p = 0.05) and heterozygous genetic model (OR = 1.28, p = 0.02)." (PMID 30147445, 2018). "A study performed for the Polish population showed the association of TLR9 1635A>G and also rs187084 polymorphisms with cervical cancer and the possible significance of these SNPs as risk factors of cervical cancer development." (PMID 23161283, 2013). "The role played by the polymorphism located in Toll-like Receptor 9 (TLR9) as a risk factor of cervical cancer remains elusive." (PMID 22714906, 2012). "We observed a contribution of the TLR9 −1486 T/C (rs187084) and C2848T (rs352140) polymorphisms to the risk of cervical cancer in a Polish population." (PMID 22714906, 2012). "Logistic regression analysis showed a significant association of the TLR9 C2848T polymorphism with cervical cancer." (PMID 22714906, 2012). "Logistic regression analysis showed a significant contribution of the TLR9 −1486 T/C polymorphism to cervical cancer." (PMID 22714906, 2012). "There are two studies on the association of the TLR9 1486 T/C (rs187084) and C2848T (rs352140) polymorphisms with cervical cancer in various populations, however, the results are inconsistent." (PMID 22714906, 2012). "Furthermore there are studies linking TLR9 (rs187084 T > C) to cervical cancer risk possibly explained by HPV infections changing the expression of toll-like receptors." (PMID 40763133, 2025). "The presence of HPV16 infection with TLR9 rs352140 SNP increased the risk of cervical cancer." (PMID 36231099, 2022). "Recent evidence suggest that TLR9 rs352140 was associated with early-stage cervical cancer." (PMID 36386838, 2022). "Furthermore, within cases, haplotypes analysis did not reveal an association of either TLR4 (Pglobal = 0.733) or TLR9 (Pglobal = 0.546) haplotypes with the early or late stages of cervical cancer." (PMID 31278284, 2019). "Interestingly, previous studies have shown that TLR2 G753A SNPs are associated with urinary tract infection, TLR4 C399T SNPs are associated with various infections and Crohn's disease, and TLR9 G2848A SNPs are associated with cervical cancer." (PMID 30116270, 2018). "Therefore, we conducted this meta-analysis to estimate the association between cervical cancer risk and the most concerning two SNPs of TLR9, rs352140 and rs187084." (PMID 30147445, 2018).
cervical carcinoma (continued). "Moreover, variations in theTLR9 gene has found associations with various diseases including cancer.TLR9 SNPs −1486 T/C and G2848A have been found to be contradictorily associated with cervical cancer risk." (PMID 30345020, 2018). "Similarly, the TLR9 c.-1486T>C SNP has been associated with cervical cancer risk in various studies." (PMID 28280748, 2017). "Therefore, we studied the association of the TLR9 −1486 T/C (rs187084) and C2848T (rs352140) polymorphisms with cervical cancer." (PMID 22714906, 2012). "Logistic regression analysis adjusting for age, pregnancy, oral contraceptive use, tobacco smoking, and menopausal status showed that both the TLR9 −1486 T/C and C2848T polymorphisms could be a genetic risk factor for cervical cancer." (PMID 22714906, 2012). "The increased expression of the TLR9 2848 T variant in precursor malignant lesion cells combined with infection by various pathogens might support inflammation and cervical cancer development." (PMID 22714906, 2012). "This may suggest that polymorphisms of TLR9 that modulate the expression of TLR9 may have an effect on the etiopathogenesis of cervical cancer." (PMID 22714906, 2012). "Our studies suggest that the TLR9 −1486 T/C and C2848T polymorphisms may be a genetic risk factor for cervical cancer." (PMID 22714906, 2012). "A comparative analysis between early (stage I + II) and late (stage III + IV) stages revealed heterozygous genotypes of TLR9 rs187084 [p = 0.011, age-adjusted OR = 0.283 (0.107–0.749)] and rs352140 [p = 0.015, age-adjusted OR = 0.304 (0.117–0.790)] to be associated with early stage cervical cancer." (PMID 31278284, 2019). "However, expression analysis of TLR4 and TLR9 genes may provide more insights into the functional role of these UTR SNPs in cervical cancer risk." (PMID 31278284, 2019). "Considering the fact that cervical cancer is largely caused by hrHPV infection and TLR9 has the ability to respond to viral DNA, while other TLRs do not, the present study was designed to elucidate the association of theTLR9 Pro99Leu polymorphism with cervical cancer." (PMID 30345020, 2018). "TLR9–1486 C allele carriers are associated with an increased risk and poor prognosis of gastric carcinoma in the Chinese population, and the 2848C/T polymorphism may be associated with Hodgkin’s lymphoma and cervical cancer." (PMID 27105145, 2016). "Therefore, we aimed to study whether TLR9 −1486 T/C (rs187084) and C2848T (rs352140) can be a genetic risk factor of cervical cancer in the Polish population." (PMID 22714906, 2012). "In HPV16-positive cervical cancer cells, TLR9, which recognizes double-stranded DNA, is downregulated due to HPV16 E6/E7 expression, similar to the effects seen with HPV38 E6/E7 proteins." (PMID 40002177, 2025). "In contrast, increased expression of TLRs, including TLR3, TLR7, TLR8, TLR9, and TLR2, has been associated with HPV16 clearance or control in cervical cancer tissues, highlighting the role of TLRs in defending against HPV infection." (PMID 40002177, 2025). "The signal transduction pathways of TLR-4 and TLR-9 single-nucleotide polymorphisms (SNPs) have been related to HPV infection and cervical cancer." (PMID 41374999, 2025). "Previous studies have demonstrated that HPV oncoproteins suppress TLR9 expression in cervical cancer epithelial cells." (PMID 39644451, 2024). "According to a study, the expression of the Toll-like receptor-9(TLR-9) gene varies depending on the stage of cervical cancer development." (PMID 37886144, 2023). "Similar results were observed in cervical cancer-derived cell lines, in which the TLR-9 expression was weaker in HPV16-positive SiHa cells and completely absent in Ca Ski cells." (PMID 36428532, 2022). "Among PRRs, toll-like receptors (TLRs), especially TLR4 and TLR9, have been extensively studied in cervical cancer and have been positively correlated with HPV16 infection." (PMID 35163748, 2022).
cervical carcinoma (continued). "It was found previously that TLR9 rs187084, as well as TLR4 rs4986790 and rs1927911 SNPs, showed an association with HPV16/18 infection in cervical cancer cases." (PMID 36231099, 2022). "It was observed that TLR9 downregulation was associated with HPV16 E6 and E7 expression in keratinocytes and in cervical cancer-derived cell lines." (PMID 35163748, 2022). "TLR4 agonist containing adjuvants have been approved as part of several vaccines: Cervarix against cervical cancer, Shingrix against shingles and Fendrix against Hepatitis B. Similarly, a TLR9 agonist is included in another Hepatitis B vaccine, Heplisav-B." (PMID 33499143, 2021). "Various TLR9 agonists based on CpG oligodeoxynucleotides are being tested in animal models of neuroblastoma, cervical carcinoma, and colon cancer and in some clinical trials." (PMID 32012718, 2020). "CC and CT genotypes of TLR4 rs11536889 and rs1927911 respectively, and TC, CC genotypes of TLR9 rs187084, as well as minor alleles of TLR4 rs4986790 and TLR9 rs187084, were associated with the increased risk of cervical cancer." (PMID 31278284, 2019). "In the present study, we investigated the role of the common TLR4 and TLR9 SNPs in susceptibility to HPV infection and cervical cancer among the study subjects from Gujarat, India." (PMID 31278284, 2019). "TLR9 promoter SNP rs187084 (-1486T/C) conferred a increased risk to HPV 16 and 18 infection and cervical cancer." (PMID 31278284, 2019). "TLR9 plays a fundamental role in pathogen recognition and the activation of innate immunity and was found to be overexpressed in cervical cancer." (PMID 30147445, 2018). "TLR9 has been the focus of numerous studies into cervical carcinoma, due to this receptor acting as a method of HPV recognition." (PMID 29416610, 2018). "To corroborate our data, we analyzed the effect of overexpressing TLR9 (using the pbabe retroviral system) in cells derived from cervical cancer patients (SiHa) positive for HPV16." (PMID 27454079, 2016). "The TLR9 C/T heterozygote frequency in women with cervical cancer was also increased compared to healthy individuals and amounted to 0.54 and 0.51, respectively." (PMID 22714906, 2012). "There was a higher frequency of the TLR9 CC genotype in women with cervical cancer compared to healthy individuals, which was 0.19 and 0.14, respectively." (PMID 22714906, 2012). "For example, a transcriptional inhibitory chromatin modification complex composed of the estrogen receptor alpha (ERα), HDAC1, JARID1B, and NF-kB transcription factor represses the expression of toll-like receptor 9 (TLR9) in the presence of E7 oncoprotein in cervical cancer cells." (PMID 34685645, 2021). "In addition, the TLR9, TLR10, and TLR5 cascades were associated with the DE genes in our study, and they were similarly dysregulated in HPV infection and cervical cancer progression." (PMID 32151264, 2020). "In contrast, high TLR9 expression was reported in cervical cancer patients in other studies." (PMID 31428574, 2019). "A few studies have attempted to address the association between TLR9 expression and cervical cancer in humans but there is a lack of consensus in the literature." (PMID 31428574, 2019). "Congruously, we observed a significant difference in the distribution of genotypes of TLR9 intronic rs352139 A/G SNP between cases and controls, however, none of its genotypes or allele was associated with cervical cancer risk." (PMID 31278284, 2019). "Since these haplotypes included both risk as well as protective alleles, a crucial role of TLR4 and TLR9 polymorphisms may be envisaged towards HPV infection and cervical cancer susceptibility." (PMID 31278284, 2019). "In addition, elevated TLR9 levels with persistent HPV infection can drive inflammation, thereby contributing to cervical cancer risk." (PMID 30147445, 2018). "Moreover, the significance of the TLR9 pathway has been demonstrated in vaccine treatment of cervical carcinoma in murine model." (PMID 22714906, 2012).
cervical carcinoma (continued). "In cervical cancer, studies have also shown increased expression of TLR9 in those patients who eliminated the virus, however this increase in TLR9 may be linked to viral clearance rather than being a characteristic feature of HPV+ cervical disease." (PMID 29416610, 2018). "Among cervical cancer cases, TLR4 and TLR9 haplotypes revealed an accumulated frequency of 85% and 83.1% respectively." (PMID 31278284, 2019). "Studies also found that TLRs, especially TLR4, TLR5 and TLR9, are closely related to HPV infection and cervical cancer." (PMID 29263932, 2017). "HPV16 E7 has also been reported to epigenetically repress the levels of TLR9, and reduced levels of TLR9 are observed in HPV16 positive keratinocyte lines and cervical cancers, suggesting that TLR9 signaling may impact HPV infection." (PMID 36016419, 2022). "TLR9 may activate UBC and NF‐κB through its signal transduction pathway and play a role in the occurrence and development of cervical cancer through the activation of NF‐kB downstream target genes." (PMID 35128835, 2022). "The pooled analysis showed that XRCC3 RS861539, TNF-α rs1800629, and IL-6 rs1800795 were associated with cervical carcinoma susceptibility, but not MTHFR rs1801133, IL-12B rs3212227 and TLR9 rs352140 polymorphisms." (PMID 34837895, 2021). "The expression of TLR5 and TLR9 is significantly increased in late-stage cervical cancer but not observed in normal cervical squamous epithelial cells." (PMID 32012718, 2020). "To identify the strong coinheritance of the SNPs we calculated linkage disequilibrium of TLR4 and TLR9 SNPs, wherein TLR4 rs10759931 and rs1927911, and TLR9 rs187084 and rs352139 were in strong LD, evincing strong influence of these inherited variations in cervical cancer." (PMID 31278284, 2019). "They observed increased mRNA expression of TLR5 and TLR9 in epithelial cells with severe SILs and cervical cancer, while in healthy cells or those with mild SIL, the mRNA expression of TLR5 and TLR9 was minimal or absent." (PMID 39273663, 2024).